IL10 (interleukin 10)
Diseases named in the same sentence as IL10 in open-access papers (continued):
Sharing a sentence is not in itself a finding about the gene and the disease.
heart failure (continued). "Here the authors show that abatacept reduces cardiomyocyte death in a mouse model of heart failure by inhibiting activation and heart infiltration of T cells and macrophages, an effect mediated by IL-10, suggesting a potential therapy for heart failure." (PMID 28262700, 2017). "IL-10 has pleiotropic effect on regulation of inflammation and low levels of IL-10 is used as a predictor of heart failure." (PMID 25954207, 2015). "TNF-α-mediated inflammation is balanced by secretion of the anti-inflammatory cytokine IL-10, and low IL-10/TNF-α are associated with pathophysiology of heart failure." (PMID 25954207, 2015). "This kind of decoy activity is thought to be of favorable contribution of IL-10 in ischemic heart after myocardial reperfusion, and it is likely to prevent against heart failure." (PMID 22529517, 2012). "The mice strains selected for these studies were from only two genotypes – heterozygous for deletion of IL-10 ("normal mice") or copper-zinc superoxide dismutase (heart failure mice)." (PMID 19454023, 2009). "Fluid overload and consecutive high venous pressure in heart failure may increase pressure in the mesothelium, which could induce the release of several inflammatory markers (IL-6, IL-10, tumor necrosis factors)." (PMID 38667440, 2024). "With respect to inflammatory markers, HF-rEF had significantly higher circulating levels of all pro-inflammatory cytokines associated with heart failure and a reduction in the protective cytokine IL-10, suggesting a greater inflammatory milieu in this type of heart failure." (PMID 36816471, 2023). "Hence, we will further focus on the methylation levels of KRAS, IL10, TLR4 and STAT3, and further determine the risk of heart failure and patient stratification by the combination of methylation and transcriptional expression in the future." (PMID 36324504, 2022). "Importantly, in patients with severe heart failure the level of serum IL-10 is significantly reduced." (PMID 33192505, 2020). "Given its manifold effects, it has to be further evaluated whether IL-10 can be used as a heart failure-specific biomarker in the future." (PMID 33330662, 2020). "Nevertheless, IL-10 is considered as a cardio-protective cytokine and increased levels of IL-10 in heart failure may be seen as a compensatory mechanism to counter deleterious effects of cytokines, such as TNF-α or IL-6." (PMID 30177883, 2018). "IL-10 can also reduce proinflammatory cytokines such as TNF-α, IL-1β, and IL-6, as well as cardiac contractility in heart failure." (PMID 39200761, 2024). "Another study showed that exercise training stimulated macrophages to induce MDSCs proliferation through IL-10/STAT3/S100A9 signaling pathway, and the increase in MDSCs significantly improved heart failure symptoms." (PMID 36761726, 2023). "Preclinical studies have provided evidence of the advantageous effects of interleukin-10 (IL-10) and transforming growth factor-beta (TGF-beta) in enhancing cardiac function and diminishing fibrosis in experimental models of heart failure." (PMID 37664375, 2023). "For example, treatment with SIN has been shown to improve stress-induced heart failure by inhibiting the expression of collagen type I and III and increasing the ratio of interleukin-10 (IL-10)/IL-17." (PMID 35837272, 2022). "It has been demonstrated that long-term exercise training can upregulate IL-10, ACE2, and Mas-R expression in the brain of SHR and heart failure models." (PMID 35250473, 2022). "Then, the high selectivity of these MNPs to pre-concentrate two kind of Heart failure biomarkers: TNF-α (2–20 ng/mL) and IL-10 (10–100 ng/mL) in a complex medium (artificial saliva) after five hours of biofunctionalization process was studied." (PMID 32878151, 2020). "Experimentally, IL-10 has been shown to act in a cardio-protective way and, amongst other mechanisms, antagonizes TNF-α, which is an important cytokine for heart failure progression." (PMID 33330662, 2020).
heart failure (continued). "Additionally, cytokines are implicated in the pathogenesis of SFTS, with elevated levels of IL-6, IL-10, TNF-α, and interferon-γ reported in severe cases, including those involving heart failure, compared to healthy adults." (PMID 38389047, 2024). "Interestingly, several paracrine factors relevant in the pathophysiology of heart failure, including IL6, IL10, NPPA and NPPB, were also expressed at higher levels in SSEA4+CD34- cells." (PMID 35709180, 2022). "In agreement with our previous work, the accumulation of LBs observed in M0, M(IFN-γ) and M(IL-10) cells was specific for TB-PE treatment given that PE from patients with heart-failure (HF-PE) failed to do so." (PMID 33002063, 2020). "Our results also demonstrated a direct correlation of IL-10 with the ejection fraction in patients with MI: IL-10 was elevated in MI+NEF group, however, the levels were significantly low in MI+LEF group suggesting an important role of IL-10 in predicting heart failure." (PMID 30356307, 2018). "An in vivo experiment using IL-10 KO and wild type mice suggested that lack of IL-10 results in adverse tissue remodeling and more severe myocardial fibrosis in an isoproterenol-induced pressure overload-derived heart failure model." (PMID 26199463, 2015).
myocarditis (62 papers, 2009 to 2025). Myocarditis is a condition that is characterized by inflammation of the heart muscle (myocardium). "Elevated levels of IL-10 have also been found in patients with acute myocarditis, after which IL-10 was suggested as a pathogenic marker that can help to discriminate acute myocarditis and AMI." (PMID 32121175, 2020). "During myocarditis, anti-inflammatory IL-10 expression was significantly lower in TSP-2 deficient mice resulting in reduced numbers of regulatory T-cells." (PMID 24376766, 2013). "Concerning IL-10, it is important to note that elevated IL-10 production is associated with control of T. cruzi and protection from fatal acute myocarditis, a condition that is much more evident in mice infected with high parasitic loads." (PMID 23951243, 2013). "CDC-EVs increase IL-10 production by Tregs to dampen systemic and local inflammation in myocarditis models." (PMID 40131367, 2025). "Such EVs from human CDCs (CDC-EVs) increase proliferation of Tregs and augment their production of IL-10, which, in turn, attenuates cardiac inflammation in rodent models of myocarditis." (PMID 40131367, 2025). "IL-10, however, modulates the inflammation intensity, mitigatingtissue damage., Our histopathologic analysisrevealed less myocarditis in Y strain-infected strains compared tothose infected with the Colombian strain." (PMID 40488037, 2025). "The other possibility involves the virus triggering immune response in the form of cytokine storm releasing IL-6, IL-10, and TNF-alpha, causing myocarditis." (PMID 36902636, 2023). "miR-98 is reported to suppress IL-10 expression in B cells of the heart, which plays an important role in myocarditis." (PMID 37391825, 2023). "We measured the levels of the proinflammatory cytokines IL-1β, IL-6, IL-8, and the regulatory cytokine IL-10 in myocarditis and control serum." (PMID 35265721, 2022). "Th2 responses can reduce acute myocarditis by promoting T regulatory (Treg) cells and secreting IL-4 and IL-10." (PMID 35198554, 2022). "IL-10, an anti-inflammatory cytokine, correlates with heart inflammation or dysfunction in cardiomyopathy, acute myocarditis, and Takotsubo cardiomyopathy." (PMID 35069538, 2021). "The mechanism of action of Tregs on CVB-associated myocarditis is likely multifaceted, as it has also been shown that secretion of the pleiotropic anti-inflammatory cytokine IL-10 also plays an important role in the amelioration of myocarditis by Tregs." (PMID 34696354, 2021). "Valproic acid, a histone deacetylase inhibitor that has anti-inflammatory effects, alleviated myocarditis in a mouse model by upregulating IL-10 in serum and heart tissues and promoting both the differentiation and suppressive function of Treg cells." (PMID 33643278, 2020). "At the same time, miRNA-98 also plays an important role in myocarditis by inhibiting the expression of IL-10 in cardiac B cells." (PMID 32582189, 2020). "Meanwhile, marked increases in Treg cells and Treg-related cytokines (TGF-β, IL-10 and IL-6) also were observed in myocarditis mice." (PMID 27724948, 2016). "Recent studies with an experimental murine model revealed not only the protective role of IL-10 against fatal myocarditis, but also demonstrated that this cytokine was produced by both CD4+ and CD8+ subsets of IFN-γ+IL-10+ double-producing T cells." (PMID 24901991, 2014). "And intravenous injection of IL-10-overexpressing monocytes/macrophages greatly reduced myocarditis and cardiac fibrosis in a murine model of autoimmune myocarditis." (PMID 24023968, 2013). "In contrast, another study emphasized the stimulation of the IL10 pathway in rats treated with fenofibrate to suppress myocarditis." (PMID 20671959, 2010). "In fact, increased levels of IL-10 in human patients with fulminant myocarditis correlates with increased mortality rates." (PMID 19587788, 2009). "Conversely, some already published papers describe the useful effect of IL-10 in myocarditis." (PMID 37627502, 2023).
myocarditis (continued). "Thus, appendectomy of mice led to increased anti-viral IFN-γ+ Th1 immune response in the intestine, decreased viral replication and reduced cardiac injury and myocarditis via down-regulating intestinal regulatory IL-10+ Treg cells." (PMID 37896753, 2023). "Regarding the pathogenesis of cardiac involvement, two hypotheses were put forth; the first highlighted the harmful heart effects of some cytokines, such as IL-8 and IL-10, affecting calcium and potassium channels and inducing myocarditis." (PMID 36454342, 2023). "When myocarditis occurred, neutrophil to lymphocyte ratio, C-reactive protein, lactate dehydrogenase, interleukin (IL)-6, IL-10, creatine kinase, MB isoenzyme of creatine kinase, and brain natriuretic peptide increased from baseline, but absolute lymphocyte count decreased." (PMID 35924238, 2022). "Our study showed that YQWY decoction could attenuate MTAC-induced myocardial inflammation, fibrosis, apoptosis, and reverse the impairment of cardiac function in rats by activating the IL-10/Stat3 signaling pathway and improving myocardium remodeling." (PMID 33456490, 2020). "In addition, the decrease in IL-10 observed can also help to explain animal death, since the genetic inactivation or immunologic neutralisation of IL-10 increases mortality and acute myocarditis in mouse models of T. cruzi infection." (PMID 31827186, 2019). "In Colombian-infected mice, IL-10 limits T. cruzi burden and protects against fatal myocarditis." (PMID 29696014, 2018). "Actually, IL-10-production by T-cells promotes T. cruzi control and protection from fatal acute myocarditis and, thus, may concur to the beneficial effects of anti-TNF in chronic infection." (PMID 25140115, 2014). "Both human KD patients and LCWE-treated mice developed coronary arteritis, myocarditis, valvulitis, and pericarditis, as well as elevated plasma levels of interleukin (IL)-2, IL-6, IL-10, monocyte chemoattractant protein (MCP)-1, and tumor necrosis factor (TNF)-α in acute phase." (PMID 22737215, 2012). "A recent study supports that at 30 dpi a proportion of infiltrating cardiac cells coexpress IL-10 and IFNγ and may play a beneficial role in T. cruzi-elicited myocarditis." (PMID 22532799, 2012). "IL-10 reduces cardiomyocyte apoptosis and increases survival in experimental myocarditis." (PMID 22174827, 2011). "In acute myocarditis triggered by cardiotropic strain of T. cruzi, IL-4 absence implies a general polarization for Th1 in the spleen, but in cardiac tissue, inflammatory balance is significantly regulated by an increase in IL-10, triggering a lower inflammatory infiltrate." (PMID 30622430, 2018). "T. cruzi infection of il10 knockout mice leads to increased levels of IFN-γ and proinflammatory cytokines, an intense myocarditis and lower survival, while higher IL-10 levels are associated with the IF of Chagas disease." (PMID 40297326, 2025). "In a previous study, in the experimental coxsackievirus-B3-induced myocarditis model, VPA treatment downregulated the expression of IL-17A and upregulated IL-10 cytokine of infected mice through the induction of Treg cell differentiation." (PMID 34067829, 2021). "However, we demonstrated in acute myocarditis triggered by T. cruzi cardiotropic strain that IL-4 absence implies a repertorial polarization for Th1, but in cardiac tissue, inflammatory balance is strongly regulated by an increase in IL-10, triggering a lower inflammatory infiltrate." (PMID 30622430, 2018). "We demonstrate that in early stages of acute phase, IL-4−/− knockout animals presented milder myocarditis with lower IFN-γ production and higher in situ IL-10 production, despite Th1 cells increase in splenocyte general repertoire." (PMID 30622430, 2018). "It has been reported that CD4 regulatory T cells can secrete regulatory cytokines (IL-10 and TGF-β) to inhibit the activities of other immunophenotypes, and thus we speculate that CD4 regulatory T cells play an important role in myocarditis." (PMID 39280093, 2024).
myocarditis (continued). "Although levels of myocarditis in our model were not different, tissue production of IL-10 was higher in the IL-32γTg group of animals." (PMID 35097133, 2022). "Consistently, adoptive transfer of female- but not male-derived M-MDSCs efficiently alleviated CVB3-induced myocarditis in male recipient mice, and this protection could be ascribed to the increased induction of regulatory and CD4+IL-10+ T cells." (PMID 26939768, 2016). "IL-10–overexpressing CD11b+ cells were injected intravenously into healthy wild-type A/J mice without induction of myocarditis." (PMID 23316321, 2012). "Finally, our findings raise the interesting possibility (albeit speculative) that tolerizing dendritic cells, which increases interleukin-10 levels, may be an effective immunomodulatory strategy for treating patients with ICI-induced myocarditis." (PMID 38205352, 2023). "Appendectomy significantly decreased intestinal IL-10 and IL-10+ CD4+ Treg frequency which led to a marked increase in intestinal (primary entry site for CVB3) anti-viral IFN-γ+ CD4+ T and IFN-γ+ CD8+ T response and viral restriction, eventually resulting in improved myocarditis." (PMID 37896753, 2023). "Thus, our data indicate that Gr-1+ cells may promote fibrogenesis and heart dysfunction in the CVB3 myocarditis model via increasing TGF-β and TNF-α-mediated inflammation while limiting IL-10 production." (PMID 29868513, 2018). "In addition, Ebi3 regulated IFN-γ-mediated myocarditis by promoting an anti-inflammatory environment through IL-10, which was most likely produced by Tr1 cells rather than classical regulatory T cells (Tregs), in the heart tissue of T. cruzi-infected animals." (PMID 29033934, 2017). "Furthermore, IL-10-secreting CD4+ cells may represent Tr1 T regulatory cells, which can suppress myocarditis induction in CVB3 infected wild-type female mice through inhibition of autoimmune T cell activation." (PMID 24816846, 2014). "IL-10 and could not be detected in the serum from myocarditis patients nor controls." (PMID 35265721, 2022). "Interestingly, short treatment with Infliximab initiated three-month postinfection diminished cardiac TNF mRNA expression and CD8-enriched myocarditis in T. cruzi-infected rats, without evidence of parasitism reactivation but in presence of increased circulating IL-10 levels." (PMID 25140115, 2014). "Thus, IL-4 absence in acute phase of experimental infection with T. cruzi Colombian strain reduces myocarditis due to lower IFN-γ production and greater IL-10 production in situ and this pattern is not influenced by splenocyte general repertoire." (PMID 30622430, 2018). "Considering the recent finding showing a role for interleukin (IL)-10 in T. cruzi-triggered myocarditis, we studied whether or not CD8+IFNγ+ cells coexpress IL-10 during T. cruzi infection." (PMID 22532799, 2012).
osteoarthritis (62 papers, 2015 to 2025). A noninflammatory degenerative joint disease occurring chiefly in older persons, characterized by degeneration of the articular cartilage, hypertrophy of bone at the margins and changes in the synovial membrane. "Furthermore, IL-2, IL-17, IL-23, TNF-β, GM-CSF, MCP-1, RANTES, eotaxin, IL-4, IL-5, IL-10 and G-CSF are also closely related with cognitive decline with ageing, synaptic or neuronal loss, osteoarthritis cancer, lung senescence." (PMID 27105505, 2016). "However, in contrast, the gene encoding IL10 itself was downregulated in our dataset (logFC = −0.74, P = 1.9 × 10−7), a finding which is consistent with the complex pattern of crosstalk between the different cytokines in osteoarthritis cartilage." (PMID 35088088, 2022). "BM-MSCs display anti-inflammatory effect by reducing IL-6, TNF-α and NF-κB, while there were increased levels of IL-10 in osteoarthritis patients." (PMID 40839685, 2025). "In the DRG, MRC1 expression has been used to identify “M2-macrophages,” which resolve osteoarthritis- or chemotherapy-induced pain by producing IL-10 or inflammatory pain by transferring mitochondria to sensory neurons." (PMID 38117255, 2024). "Recently, a randomized double-blind placebo-clinical trial by arthrocen showed that its oral administration diminished TNF-α and IL-17 while it increased anti-inflammatory IL-4 and IL-10 blood levels in patients with osteoarthritis." (PMID 38402151, 2024). "In this regard, Velloso Alvarez et al19 showed that ACS is a strategy to improve the clinical symptoms of horses with osteoarthritis so that 50% ACS increases IL-10 expression and decreases IL-1β in cartilage." (PMID 37645547, 2023). "Curcumin reportedly reduces osteoarthritis (OA) joint degeneration by stimulating autophagy and/or increasing the expression of IL10, which reduces matrix metalloproteases (MMPs) that degrade the ECM of cartilage." (PMID 36835255, 2023). "IL-10 inhibits cell apoptosis by suppressing activated caspase-3 levels and bax/bcl-2 ratio to improve the osteoarthritis process." (PMID 36768679, 2023). "Not only has IL-10 been shown to upregulate Treg cells, it is a potent anti-inflammatory cytokine that plays a role in the pathogenesis of osteoarthritis." (PMID 36090170, 2022). "Jhun and collaborators showed that a combination of L. acidophilus LA-1, vitamin B and curcumin downregulated Th17 cells and IL-17, while the production of IL-10 was increased in human PBMCs isolated from osteoarthritis patients." (PMID 35408849, 2022). "Tobetter understand the mechanisms behind its potential as DMOAD, thissystematic narrative review aims to assess the potential of IL-4, IL-10 andthe combination of IL-4 and IL-10 for the treatment of osteoarthritis." (PMID 35549461, 2022). "IL-10 inhibits cell apoptosis by suppressing activated caspase-3 levels and the ratio of bax/bcl-2 to ameliorate the process of osteoarthritis." (PMID 36186138, 2022). "A fusion protein of interleukin-4 and interleukin-10 (IL4-10 FP) wasdeveloped as a disease-modifying osteoarthritis drug (DMOAD), andchondroprotection, anti-inflammation, and analgesia have been suggested." (PMID 35549461, 2022). "In another pro-inflammatory disorder, osteoarthritis, increased IL-10 expression significantly decreased pain in a dog model, supporting the benefits of IL-10 prophylactics for inflammatory conditions." (PMID 35096797, 2021). "KGN also regulated the reciprocal balance between proinflammatory cytokine production, including interleukin-10 and -1β, in joints in experimental osteoarthritis murine model." (PMID 30218055, 2018). "The secretion of G-CSF, VEGF, IL-6, and IL-10 were determined in cell-free supernatants of 3D-cultured synovial explants from three individual osteoarthritis patients." (PMID 29922175, 2018).